MCL1 (MCL1 apoptosis regulator, BCL2 family member)
Diseases named in the same sentence as MCL1 in open-access papers (continued):
Sharing a sentence is not in itself a finding about the gene and the disease.
cancer (continued). "Chemotherapy-resistant cancer cells are characterized by the overexpression of members of the anti-apoptotic B-cell lymphoma 2 (Bcl-2) protein family, such as Bcl-XL, Bcl-2, and Mcl-1." (PMID 31798573, 2019). "Actually, there are such previous studies showing that BH3 mimetics had drug resistances by compensatory activity of Mcl-1 for the inhibition of Bcl-2/Bcl-xL and Mcl-1 activation sensitized cancer cells to BH3 mimetics." (PMID 32257914, 2019). "We have recently shown that an intermittent weekly or twice weekly schedule of a potent short-acting pharmacological inhibitor of MCL1 is well tolerated in animal models and active against a range of cancers in vivo, including AML." (PMID 30214012, 2019). "It is certified that Mcl-1 can promote cancer metastasis and resistance to conventional chemotherapy, and thus is correlated with poor prognosis." (PMID 31601252, 2019). "MCL1 remains an attractive target because, in addition to eliciting drug resistance, it is frequently increased in cancer and contributes to tumorigenesis and metastasis." (PMID 30796196, 2019). "The anti-apoptotic proteins, including BCL2, BCLXL, BCLW, MCL1 and A1, protect cells from chemotherapy drug-induced apoptosis and are dysregulated in many cancers." (PMID 31467488, 2019). "Cancer cells, however, are able to evade death by increasing the level of proteins that block apoptosis, such as MCL1." (PMID 31294695, 2019). "MCL-1 is an anti-apoptotic member of the Bcl-2 protein family and a key factor in conferring resistance to some cancer types to conventional chemotherapy." (PMID 31620362, 2019). "Sensitization of cancer cells to anti-cancer drug-induced apoptosis is related with down-regulation of apoptosis related proteins (Mcl-1 or Bcl-2) and inhibition of phosphorylation of STAT3." (PMID 31817696, 2019). "Studies found that MCL-1 major anti-apoptotic protein was frequently overexpressed and identified as an important target in majority of human cancers." (PMID 31191820, 2019). "Not only is its increased expression critical for oncogenesis and cancer progression, but Mcl-1 is also involved in conferring chemotherapeutic drug resistance in this cancer." (PMID 31117253, 2019). "Further, NOXA has been shown to induce apoptosis under glucose deprivation or by glycolysis inhibition by glucose analog 2-deoxy glucose (2-DG) with concordant decline in MCL-1 levels in different cancers." (PMID 31405035, 2019). "Mcl-1 was not only shown to protect cells against apoptotic stimuli, but also this protein has been suggested as an important therapeutic target in human cancers." (PMID 31117253, 2019). "In our study we found that mir-29a downregulation will lead to the overexpression of MCL1, an anti-apoptotic gene that helps in survival of cancer cells and inhibits apoptosis." (PMID 31870103, 2019). "Inhibitors targeting MCL1 are in clinical development, however numerous cancer models are intrinsically resistant to this approach." (PMID 31294695, 2019). "FLG interacts with MCL1, USP1, C21orf59, MAK, and KIR3DS1 and mucin interacts with ERBB3, SNAI1, TWIST1, TWIST2, and CDH2, all of which, IPA predicted to be associated with cancer." (PMID 31058088, 2019). "To confirm that targeting MCL-1 would be beneficial by impacting both on bCAFs and on bCAFs influenced cancer cells, we used co-cultures of these two cell types challenged with BH3 mimetics." (PMID 30631150, 2019). "bCAFs favor MCL-1 expression and apoptotic resistance in luminal cancer cells in a IL-6 dependent manner while their own, robust, survival also relies on MCL-1." (PMID 30631150, 2019).
cancer (continued). "Some of the most potent antiapoptotic factors influencing ERα expression and cancer cell survival, are the members of the Bcl-2 gene family, including myeloid cell leukemia-1(Mcl-1)." (PMID 31763216, 2019). "In fact, overexpression of Mcl-1 is a major mechanism of cancer cell resistance to ABT-737 treatment." (PMID 31092272, 2019). "In parallel, given the important role of MCL1 in neoplasm, we conducted TCGA pan-cancer genomic interrogation of copy number alterations and somatic mutations for the tested 84 human DUBs." (PMID 29335437, 2018). "The anti-apoptotic MCL-1 is a key regulator in cancer cell survival, and can be a therapeutic target." (PMID 30201893, 2018). "Drugs targeting Mcl-1, and other Bcl-2 pro-survival proteins, are being developed as cancer therapies, and some of these inhibitors have advanced to clinical trials." (PMID 29928066, 2018). "Using this approach, we mapped cellular dependencies and co-dependencies on BCL-2, BCL-XL, and MCL-1 across a large number of primary and established cancer cell lines representing 10 distinct cancer types." (PMID 30158527, 2018). "Further RT‐qPCR analysis showed that MCL1 mRNA was initially inhibited in all three cancer cell lines at 4 h but was substantially increased in HT29 and RKO cells by both seliciclib and CCT068127 at 24–48 h." (PMID 29063678, 2018). "Mcl-1 is a member of the Bcl-2 family of proteins that promotes cell survival by preventing induction of apoptosis in many cancers." (PMID 30559424, 2018). "Upregulation of MCL-1 expression upon treatment with navitoclax or ABT737 has been previously reported as a mechanism of resistance in various cancer cells." (PMID 30123424, 2018). "Mcl-1 promotes cell transformation, cancer survival, and resistance to chemotherapy, and selective Mcl-1 inhibitors competitively engage its binding groove, mimicking the structural mechanism of action of native sensitizer BH3-only proteins." (PMID 30386247, 2018). "Many cancer cells are apt to be resistant to chemotherapeutic agents due to overexpression of prosurvival factors, such as Mcl-1, Bcl-2, and Bcl-xL." (PMID 29416631, 2018). "XPO1 is a nuclear exporter overexpressed in AML cells and its inhibition decreases Mcl‐1 levels in cancer cells." (PMID 30596398, 2018). "Further studies identified that the pro-apoptotic effect of PTBP1 under mitotic stress induced by antitubulin drugs vincristine and docetaxel results from its suppression of MCL1 expression in cancer cells." (PMID 29361709, 2018). "Mcl-1, a member of Bcl-2 family proteins, has been found frequently overexpressed in multiple cancer types." (PMID 29899555, 2018). "Mcl-1 is an antiapoptosis factor and has been demonstrated to be re-regulated in many types of cancer and has been reported to be indicators of prognosis and overall survival." (PMID 29736179, 2018). "Together, our data demonstrate that (Ra)-7 kills cancer cells by specific and direct inhibition of Mcl-1 that triggers disruption of the Mcl-1-Bak complex and subsequent activation of the Bak-dependent mitochondrial apoptotic pathway." (PMID 30559424, 2018). "Depletion of Pin1 results in up-regulation of FBXW7 and reduced levels of FBXW7 substrates such as Mcl-1, and sensitizes cancer cells to the chemotherapy drug Taxol." (PMID 30086763, 2018). "The anti-apoptotic protein, myeloid cell leukaemia-1 (Mcl-1), is frequently overexpressed in a variety of human cancers, mediating their survival and resistance to chemo- and targeted therapy." (PMID 29976942, 2018). "Co-amplification of MYC with MCL-1 or BCLX is common in cancer and in cell culture and mouse models increased BCL-2-like proteins, and MYC is a potent oncogenic combination." (PMID 29769323, 2018). "Overexpression of MCL1 has been identified as a key contributor to tumorigenesis, and further enables resistance to a number of anti-cancer chemotherapies." (PMID 29748555, 2018).
cancer (continued). "In our study, we determined that H89/tetrandrine treatment synergistically inhibited Mcl-1 in cancer cells at both the transcription and protein expression levels." (PMID 29866132, 2018). "Mcl-1 ectopic expression significantly diminished H89/tetrandrine sensitivity and amplified c-Myc sensitized cancer cells in the combined treatment." (PMID 29866132, 2018). "Mcl-1 has become a well-validated therapeutic target, promoting the development of new anti-cancer therapies." (PMID 29976942, 2018). "In many cancer cells, overexpression of prosurvival factors, such as Bcl-2, Bcl-xL, and Mcl-1, contributes to resistance to anticancer agents." (PMID 29642569, 2018). "We sought to further investigate cancer-associated alterations of USP13 and MCL1 in more detail and determine the clinical relevance of USP13-MCL1 regulatory axis." (PMID 29335437, 2018). "MCL-1 is a very short half-life protein in comparison to other Bcl-2 family members, making it a promising target for cancers." (PMID 29899871, 2018). "Here, we have described several microRNAs targeting MCL-1 that have been shown to sensitize cancer cells to cytotoxicity induced by either chemotherapeutics (miR-125b, miR-101, miR-519d) or TRAIL (TNF-related apoptosis-inducing ligand) treatment (miR-29)." (PMID 29570632, 2018). "In this regard, repurposing cancer therapeutics that target Mcl-1 becomes a viable strategy for limiting M. tb growth in human macrophages and TB granulomas." (PMID 29928066, 2018). "Recent studies suggest that Mcl-1 can inhibit autophagy and play critical roles in cancer cell survival and death." (PMID 29899555, 2018). "Increased transcription of pro-survival proteins can also elevate their expression in cancer and increased transcription/translation seems important for regulation of MCL-1 levels." (PMID 29769323, 2018). "MCL1, as a key anti-apoptotic protein, is commonly overexpressed in cancers and selective MCL1 inhibitors have shown significant effects in in vivo and in vitro cancer models." (PMID 29748555, 2018). "Anti-apoptotic Bcl-2 family protein Mcl-1 has been identified as an important target for sensitizing cancer cells to ABT-737." (PMID 29543705, 2018). "Downregulation of MCL-1 by miRNAs was found to affect also the cancer stem cell (CSC) population in breast cancer." (PMID 29570632, 2018). "A number of studies have revealed that miR-193b triggers apoptosis in various cancer cells via downregulation of MCL-1." (PMID 29719597, 2018). "While Mcl-1 is pivotal for survival of cancer cells, more recently its localization in the mitochondrial matrix was uncovered, modulating directly OXPHOS and helping to drive oxygen dependent ATP production." (PMID 29743557, 2018). "Many anti-apoptotic proteins play an important role in hematological malignancies and in solid tumors because of their upregulation, among them MCL-1 protein, leading to resistance to apoptosis in cancers." (PMID 29899871, 2018). "Interleukin 6 (IL-6) up regulates myeloid cell leukemia-1 (Mcl-1), a protein that is important in the anti-apoptotic factors in the development of cancer in the biliary epithelial cells." (PMID 30613437, 2018). "In mice, MCL-1 inhibitor S63845 was tolerated well at concentrations that killed cancer cells, even when murine Mcl-1 was replaced by its human ortholog, thereby increasing inhibitor sensitivity of all cells." (PMID 30524962, 2018). "It has been demonstrated that gossypol binds to the BH3 binding groove of anti-apoptotic Bcl-2 proteins, thus inhibiting the anti-apoptotic function of Bcl-2, Bcl-xl, and Mcl-1, and inducing apoptosis of cancer cells." (PMID 30459622, 2018). "A common trend found among various types of cancers is a decrease in pro-apoptotic Bax and Bak and an increase in anti-apoptotic Bcl-2, Mcl-1, and Bfl-1 levels." (PMID 29904021, 2018). "Inactivation of Mcl-1 either by decreasing its expression or binding to pro-apoptotic proteins restores ABT-263 sensitivity in cancer cells." (PMID 29520102, 2018).
cancer (continued). "Gossypol binds to the BH3 binding groove of anti-apoptotic Bcl-2 proteins, thus inhibiting the anti-apoptotic function of Bcl-2, Bcl-xl, and Mcl-1, and inducing apoptosis of cancer cells." (PMID 30459622, 2018). "Small molecule inhibitors of CDK9 have been shown to induce apoptosis in cancer cells by suppressing Mcl-1." (PMID 28520795, 2017). "Among the candidates, genes of c-met and MCL-1, which have been reported to be associated with TRAIL sensitivity to several cancers, were commonly predicted by all of these databases and contain complementary sequences paired with miR-101 at the 3’ UTR." (PMID 29312559, 2017). "Mcl-1 is an important anti-apoptotic protein that promotes survival of many cancers and confers resistance to therapeutic agents." (PMID 28301598, 2017). "Mcl-1 is an anti-apoptotic member of the Bcl-2 family, and it is up-regulated in a variety of human cancers and highly expressed in many human cancer cell lines." (PMID 29254209, 2017). "In these studies, high endogenous levels of MCL1 have been reported to contribute to resistance to the cancer killing potential of BH3 mimetics." (PMID 28915653, 2017). "The proof of concept is demonstrated with the apoptosis regulator Mcl‐1, commonly exploited by cancers to avoid cell death." (PMID 28670766, 2017). "Mcl-1 small molecular inhibitors, such as A-1210477 and S63845, have been proved to potently eliminate various kinds of Mcl1-dependent cancer cells." (PMID 29383093, 2017). "A subset of the identified in vitro binders was found to possess activity towards cancer cell lines that overexpress Mcl‐1 and induce hallmarks of the apoptosis pathway." (PMID 28670766, 2017). "Mcl-1 is a well-known marker of anti-apoptosis whose role in cancer drug resistance is well documented." (PMID 28520795, 2017). "Erk, a kinase involved in cancer cell survival, phosphorylates Mcl-1 which prevents proteasomal degradation of Mcl-1." (PMID 28187444, 2017). "Overexpression of MCL-1 is frequently resistance to various cancer therapies, including chemotherapy." (PMID 28659182, 2017). "MCL1, a member of the Bcl-2 family, is an antiapoptotic protein frequently overexpressed in cancer cells." (PMID 29290969, 2017). "Against this background, we analyzed the expression of the anti-apoptotic BCL-2 family members BCL-2, BCL-XL and MCL-1 in our cancer models with conditional pathway activation." (PMID 28507280, 2017). "Its dual activity has been validated to reduce PUMA-dependent apoptosis while deactivating Mcl-1-mediated anti-apoptosis in cancer cells." (PMID 28903337, 2017). "In these cancer cells, Mcl-1 interacted with VDAC, with a pronounced role for its N-terminus, thereby increasing mitochondrial Ca2+ uptake, resulting in increased ROS production and cell migration." (PMID 28516063, 2017). "Previous study has indicated that cancer cells with higher Bim and lower Mcl-1 expression is more sensitivity to ABT-263." (PMID 29156797, 2017). "Many cancer cells have increased levels of Mcl-1 protein due to the misregulation of cellular UPS factors like MULE, USP9X and components of the SCFFbw7 complex which promotes apoptosis resistance." (PMID 28347402, 2017). "The importance of Noxa and Mcl-1 as drug targets in cancer therapy is becoming increasingly evident." (PMID 28892004, 2017). "FBXW7 can target the degradation of MCL1,cyclin E,Notch,c-Jun and c-Myc, cancer genes related to the proliferation and regulation of gastric cancer cells." (PMID 28464881, 2017). "Intriguingly, in our study, cancer cells responded to subcytotoxic sunitinib doses by activating mTORC1 and increasing Mcl-1 protein levels." (PMID 29066973, 2017). "Identification of TDRD3 as a regulator of USP9X is important because it provides an alternative pathway to target MCL-1 in cancer." (PMID 28101374, 2017). "The regulation of Mcl-1 expression is necessary for the induction of cancer cell apoptosis by ABTs such as ABT-737, ABT-263 and ABT-199." (PMID 28038464, 2017).
cancer (continued). "Controversely, Mcl-1 can be up-regulated by ABT-263 which contributes to ABT-263 resistance in cancer cells." (PMID 28464919, 2017). "Combined inhibition of BCL-2, BCL-XL and MCL-1 through mechanism-guided combination therapy will provide the most effective and a potentially universal therapeutic strategy to eradicate cancer cells through apoptotic induction." (PMID 28714472, 2017). "MCL-1 is one of the most widely expressed pathologic factors in human cancers, and many putative MCL-1 inhibitors have been synthesised, several of which have demonstrated selectivity in different types of in vitro assays." (PMID 28079887, 2017). "Non-IAP anti-apoptotic proteins of the Bcl-2 family such as myeloid cell leukemia-1 protein (Mcl-1), are known to also mediate drug resistance in diverse cancers." (PMID 28520795, 2017). "Mcl-1, a Bcl-2 family member, is highly expressed in a variety of human cancers and is believed to enhance tumorigenic potential and chemotherapy resistance through the inhibition of apoptosis and senescence." (PMID 28423654, 2017). "MCL-1 is one of the major pro-survival genes that are expressed at high levels in many types of cancer." (PMID 28101374, 2017). "Even if CGs modulate the expression of several Bcl-2 family proteins, their strongest and most ubiquitous effect in cancer cell lines was the modulation of Mcl-1." (PMID 29117117, 2017). "This is consistent with several studies over the last decade that have focused on Mcl-1 as a key anti-apoptotic protein mediating drug resistance in various human cancers." (PMID 28520795, 2017). "The MCL-1 locus is one of the “top ten” most amplified genomic regions in a variety of human cancers, correlating with an upregulation of MCL-1 activity." (PMID 27086916, 2017). "Compounds show selectivity for Mcl‐1 over other anti‐apoptotic proteins, possess cytotoxicity to cancer cell lines, and induce hallmarks of apoptosis." (PMID 28670766, 2017). "PEA-based immunotoxins inhibit the protein biosynthesis of antigen-expressing cancer cells and especially downregulate Mcl-1." (PMID 28868037, 2017). "4E-BP1 phosphorylation is known to enable the translation initiation of Mcl-1, a critical protein for cancer cell survival." (PMID 29290965, 2017). "Cancer cells can evade apoptosis by the up-regulation of the pro-survival Bcl-2 family proteins such as Bcl-2, Bcl-xl, and Mcl-1." (PMID 28464919, 2017). "Previous studies showed that cancer cells with high Bim/Mcl-1 ratios were sensitive to ABT-263 treatment." (PMID 29156797, 2017). "A pro-apoptotic role for miR-29b in the context of MCL-1 has been shown previously for a number of cellular models and diseases including cancer, diabetes and pre-eclampsia." (PMID 28190086, 2017). "The targeting of survival proteins like Mcl-1 and the other Bcl-2 family members for cancer therapy is the subject of ongoing scientific and commercial interest." (PMID 28423654, 2017). "While activation of Mcl-1 leads to survival of cancer cells, inhibition of Mcl-1 has been found to eliminate a series of cancer cells." (PMID 28903337, 2017). "In another study, it was explored in vitro and in pre-clinical models that miR-519d increases the sensitivity to cisplatin by targeting MCL-1 (Myeloid cell leukemia 1)—an important anti-apoptotic protein in cancer—in BC stem cells." (PMID 28574440, 2017). "Mcl-1 plays a critical role in the survival of multiple cell types and is one of the highly amplified genes in cancer." (PMID 29383093, 2017). "Mcl-1 is overexpressed in many cancers and has been a very attractive drug target for treating cancer." (PMID 29383093, 2017). "It was reported that modulation of Noxa and Mcl-1 was important for compound-induced anti-cancer effects." (PMID 28892004, 2017). "Aberrant MCL-1 overexpression in numerous human cancers has been shown to result in increased proliferation, tumor cell survival, drug resistance and metastasis." (PMID 27063186, 2016).